FBXW9 (F-box and WD repeat domain containing 9)
Description:
Substrate-recognition component of the SCF (SKP1-CUL1-F-box protein)-type E3 ubiquitin ligase complex.
Synonyms: FBW9; MGC10870; MEC-15
Tractability: PROTAC: ubiquitination databases record sites on it; its protein half-life has been measured.
Gene: Protein-coding gene on chromosome 19 (12,688,053 to 12,696,649, reverse strand). Ensembl gene ENSG00000132004.
Subcellular location (Human Protein Atlas): Cytosol
Pathways (Reactome):
Metabolism of proteins: Association of TriC/CCT with target proteins during biosynthesis; Neddylation
Immune System: Antigen processing: Ubiquitination & Proteasome degradation
Gene Ontology:
Molecular function: protein binding
Biological process: SCF-dependent proteasomal ubiquitin-dependent protein catabolic process
Cellular component: cytosol; SCF ubiquitin ligase complex
Genetic constraint (gnomAD): Loss-of-function variants: 38 observed, 56.82 expected, observed/expected ratio (o/e) 0.67, 90% interval 0.51 to 0.88. The upper end of that interval is the gene's LOEUF score, 0.88, which puts it in group 3 of 6, group 1 being the genes least tolerant of losing a copy. Missense variants: 590 observed, 623.96 expected, observed/expected ratio (o/e) 0.95, 90% interval 0.88 to 1.01. Synonymous variants: 289 observed, 276.02 expected, observed/expected ratio (o/e) 1.05, 90% interval 0.95 to 1.15.
Homologues: Orthologues: chimpanzee FBXW9 (97% identical), macaque FBXW9 (91% identical), dog FBXW9 (82% identical), pig FBXW9 (82% identical), rat Fbxw9 (78% identical), guinea pig FBXW9 (78% identical), mouse Fbxw9 (78% identical), tropical clawed frog fbxw9 (53% identical), zebrafish fbxw9 (38% identical). Paralogues in human: FBXW7 (21% identical), FBXW11 (18% identical), BTRC (18% identical), WDR49 (16% identical), WDR86 (15% identical), TRAF7 (14% identical), EFCAB8 (14% identical), WDR64 (14% identical), FBXW12 (11% identical), FBXW8 (9% identical), PAAF1 (9% identical), WDR54 (8% identical), and 2 more.
Diseases named in the same sentence as FBXW9 in open-access papers:
FBXW9 is named in the same sentence as 14 diseases in open-access papers, as found by Europe PMC text mining. Sharing a sentence is not in itself a finding about the gene and the disease. The quoted sentences say what the papers report.
bladder cancers (1 paper, 2024). "High expression of FBXW9 was associated with good OS (HR = 0.36, p = 0.0046) in PRCC and poor OS in breast and bladder cancers." (PMID 38893126, 2024).
bladder urothelial carcinoma (1 paper, 2023). "Noticeably, the most significant upregulation of FBXW9 was observed in invasive breast carcinoma (BRCA) (p = 9.10 × 10−19), followed by colon adenocarcinoma (COAD) (p = 2.30 × 10−18), bladder urothelial carcinoma (BLCA) (p = 7.60 × 10−10), and 11 other cancer types (p < 0.001 for all)." (PMID 36982338, 2023).
breast carcinoma (1 paper, 2023). "The data support a potential role of FBXW9 in breast cancer stem cells that needs further experiments for validation." (PMID 36982338, 2023). "Due to the critical role of cancer stem cells in mediating chemotherapy resistance, we next analyzed the association between FBXW9 expression and relapse-free survival (RFS) of patients with breast cancer." (PMID 36982338, 2023). "We also performed cell-based assays to validate the pro-cancer function of FBXW9 in breast cancer cells." (PMID 36982338, 2023). "Our study highlights the potential role of FBXW9 as a biomarker and promising target for patients with breast cancer." (PMID 36982338, 2023). "In the present study, via integrative analysis of transcriptome profiles from The Cancer Genome Atlas (TCGA) datasets, we found that FBXW9 was upregulated in the majority of cancer types, including breast cancer." (PMID 36982338, 2023). "In breast cancer cells, we confirmed that the knockdown of FBXW9 inhibited cell proliferation and induced the arrest of cell cycle progression." (PMID 36982338, 2023). "Via analysis of transcriptome data of breast cancer, FBXW9 was related to the activities of several cell cycle regulators including MYC and ESR1." (PMID 36982338, 2023). "Cell-based assays showed that silencing of FBXW9 inhibited cell proliferation and cell cycle progression in breast cancer cells." (PMID 36982338, 2023). "mRNA levels of FBXW9 and FBXW4 were negatively associated with stroma score (p < 0.001) in breast cancer." (PMID 36982338, 2023). "Moreover, we confirmed the protein expression of p21 was increased in breast cancer cells upon FBXW9 silencing." (PMID 36982338, 2023). "We experimentally found that FBXW9 repressed the expression of NECTIN2, a regulator of the tumor microenvironment, in breast cancer cells." (PMID 36982338, 2023). "Indeed, the knockdown of FBXW9 increased p21 mRNA expression while mRNA levels of CCNA2 and CCNB1 were decreased in breast cancer cells." (PMID 36982338, 2023).
breast tumors (1 paper, 2023). "We further evaluated FBXW9 mRNA expression in our collected breast tumors, which also showed upregulation of FBXW9 mRNA in tumors compared with normal tissues." (PMID 36982338, 2023).
cervical squamous cell carcinoma (1 paper, 2023). A squamous cell carcinoma arising from the cervical epithelium. "In contrast, low or medium staining of FBXW9 protein was observed in tumors of corresponding types (BLCA, BRCA, and cervical squamous cell carcinoma and endocervical adenocarcinoma (CESC))." (PMID 36982338, 2023).
glioblastoma (1 paper, 2025). The most malignant astrocytic tumor (WHO grade IV). "Moreover, in glioblastoma, the binding of insulin-like growth factor-binding protein 5 (IGFBP5) to ROR1 facilitates the formation of a ROR1/HER2 heterodimer, which subsequently induces the expression of genes like ETV5 and FBXW9 to promote glioblastoma stem-like cell invasion and tumorigenesis." (PMID 40869147, 2025).
glioma (1 paper, 2023). A benign or malignant brain and spinal cord tumor that arises from glial cells (astrocytes, oligodendrocytes, ependymal cells). "Given the potential involvement of IGFBP5, ETV5, and FBXW9 in the invasive potential of GSCs, we subsequently aimed to identify associations between the expression of these three genes and patient survival using TCGA glioma datasets." (PMID 36949068, 2023). "Although our analysis revealed a considerable level of correlation between high ETV5 or FBXW9 expression and poor prognosis in patients with glioma, further studies are required to reveal the mechanical role of ETV5 and FBXW9 in GSC invasion and tumorigenesis." (PMID 36949068, 2023). "By analyzing the patient survival rates in TCGA glioma datasets, we elucidated the clinical significance of the regulation of ETV5 and FBXW9 by IGFBP5." (PMID 36949068, 2023). "Therefore, the increase ETV5 and FBXW9 expression in response to IGFBP5 has a negative impact on the survival of patients with glioma." (PMID 36949068, 2023).
rectum adenocarcinoma (1 paper, 2023). An adenocarcinoma arising from the rectum. "In contrast, high expression of FBXW9 was associated with good prognosis in rectum adenocarcinoma (READ) (HR = 0.36) and kidney renal papillary cell carcinoma (KIRP) (HR = 0.36)." (PMID 36982338, 2023).
tumor (4 papers, 2023 to 2025). "The expression of FBXW9 in pan-cancer and normal tissues was found to be increased in tumor tissues compared to that in normal tissues of PRCC patients." (PMID 38893126, 2024). "The knockdown of IGFBP5 expression in 772 GSCs suppressed GSC invasion, as well as the expression of the target genes ETV5 and FBXW9, and tumor volume, while significantly prolonged the survival of the mouse." (PMID 36949068, 2023).
cancer (3 papers, 2022 to 2024). A tumor composed of atypical neoplastic, often pleomorphic cells that invade other tissues. "Compared with other members, the expression of FBXW9 was associated with overall survival in more cancer types." (PMID 36982338, 2023). "Interestingly, the current pan-cancer analysis also provided novel findings uncovering the upregulation of FBXW9 in the majority of cancer types examined, as well as the downregulation of FBXW11 in multiple cancer types." (PMID 36982338, 2023). "While, FBXW9 had a detrimental role in other three cancers including LIHC, ACC, and LGG." (PMID 36591289, 2022). "FBXW9 might govern cell cycle, stemness, and immune infiltration in cancers." (PMID 36982338, 2023). "Importantly, the data strongly suggested a critical role of FBXW9 in several cancer types." (PMID 36982338, 2023). "Of all FBXW members, FBXW9 was the most frequently upregulated across 17 cancer types (14/17), while FBXW11 was the most frequently downregulated gene in cancers (10/17)." (PMID 36982338, 2023). "Additionally, FBXW9 was positively correlated with the activity of MYC signaling according to RABIT transcription factor regulatory impact, which is a well-known contributor to cancer stemness." (PMID 36982338, 2023).
FBXW9 also shares sentences with these, for which no sentence is quoted: colon adenocarcinoma (1 paper); endocervical adenocarcinoma (1); invasive breast carcinoma (1); ovarian carcinoma (1).